INS (insulin)
Diseases named in the same sentence as INS in open-access papers (continued):
Sharing a sentence is not in itself a finding about the gene and the disease.
type 2 diabetes (continued). "It is involved in the pathogenesis of insulin-resistant states and is targeted by metformin, an insulin sensitizer, for the treatment of type 2 diabetes." (PMID 34930403, 2021). "TZDs improve insulin sensitivity in peripheral tissues and ameliorate glucose tolerance and insulin sensitivity in type 2 diabetic patients." (PMID 34712628, 2021). "Impairment of tissue insulin sensitivity in type 2 diabetes is a significant factor for sudden cardiac death." (PMID 34692349, 2021). "It has been shown that training under hypoxic conditions improves glucose tolerance and insulin sensitivity in patients with type 2 diabetes and obese persons with metabolic syndrome compared to patients training under normoxic conditions." (PMID 34948667, 2021). "DPP-4 inhibitors are known to be effective in the treatment of type 2 diabetes by regulating insulin and glucagon secretion with few major side effects." (PMID 34205264, 2021). "Thus, reducing phenotypic heterogeneity by characterisation of type 2 diabetes subgroups with predominately insulin deficiency or insulin secretion may be a good starting point to further study the associations between genetic markers and glycaemic response to novel glucose-lowering drugs." (PMID 33594477, 2021). "More recently, a number of experimental studies have reported beneficial effects of CAR agonism in type II diabetes and obesity by improving glucose tolerance, insulin sensitivity, inducing β-oxidation and reducing lipid deposition." (PMID 34502180, 2021). "The high insulin level in obesity and type 2 diabetes is related to the occurrence and development of various tumors." (PMID 34485124, 2021). "Two examples are the insulin-sensitizing troglitazone, used to treat patients with type 2 diabetes, and the fibrate fenofibrate, mainly used in the treatment of hypertriglyceridemia." (PMID 33498870, 2021). "Both dietary regimens were safe for individuals with type 2 diabetes or high BP or both, as well as for people using insulin and/or sulfonylureas." (PMID 34733895, 2021). "At the onset of diabetes type 2 the pancreas is still able to produce insulin and the serum level of insulin is high in this conditions." (PMID 34670596, 2021). "Many patients with type 2 diabetes will ultimately require the inclusion of basal insulin in their treatment regimen." (PMID 34165382, 2021). "In patients with type 2 diabetes, insulin regimens are normally administered in combination with oral antidiabetic drugs (OADs)." (PMID 34174848, 2021). "Low testosterone (T) levels lead to reduced glucose tolerance and insulin activity (insulin resistance), particularly in elderly men —effects which are correlated with type 2 diabetes." (PMID 33513940, 2021). "In subjects with type 2 diabetes, both the insulin signaling pathways are impaired in the skeletal muscle, resulting in a reduction of insulin-induced glucose uptake by the skeletal muscle." (PMID 34417555, 2021). "In type 2 diabetes, pancreatic islets have around 60% decrease in β‐cell mass and present impaired glucose stimulated insulin secretion (GSIS) capacity." (PMID 34319011, 2021). "These include MLKL in endosomal trafficking, insulin sensitivity, and type II diabetes or the requirement for MLKL for myelin sheath breakdown." (PMID 34079078, 2021). "In the HOME trial 390 insulin-treated patients with type 2 diabetes were randomized to 850 mg metformin or placebo three times daily." (PMID 33830998, 2021). "In type 2 diabetes, the body develops a resistance to insulin, resulting in a decrease in the amount of glucose that can be removed from the blood and stored as glycogen." (PMID 33458612, 2021). "STZ exerts selective cytotoxic activity upon insulin-producing β-cells in the pancreas, which inducing both type 1 and type 2 diabetes." (PMID 33435282, 2021).
type 2 diabetes (continued). "Canagliflozin when added to subjects with Type 2 Diabetes along with metformin and/or Insulin, demonstrates a functional improvement of CD34+ Endothelial Progenitor Cell migratory function through increased CD34/CXCR4 positivity." (PMID 33581737, 2021). "Defects in both the availability and action of insulin lead to elevated plasma glucose levels and are major hallmarks of type-2 diabetes." (PMID 33146746, 2021). "Injections of insulin are important to treat both type 1 and type 2 diabetes, and recombinant human insulin has been shown to have significant advantages over insulins extracted from pork and beef sources." (PMID 34336550, 2021). "Studies have shown that the onset of type 2 diabetes is related to ROS: glycation and the consequent increase of ROS can inhibit the transcription of insulin genes in mouse β-cell–derived HIT-T15 cells." (PMID 35185542, 2021). "People suffering from obesity tend to develop conditions, such as cardiovascular disease, hypertension, insulin dysfunction, and type II diabetes." (PMID 34299638, 2021). "Increasing insulin sensitivity by controlling Nrf2 levels is a potential avenue to treat type 2 diabetes." (PMID 34829154, 2021). "In type 2 diabetes with poor glycemic control, the hepatic glucose output is regulated by gluconeogenesis, through changes in the levels of insulin, insulin counter-regulatory hormones, and the supply of gluconeogenic substrates." (PMID 34526589, 2021). "Mild cold acclimation for 10 days has been previously shown to markedly improve insulin sensitivity in patients with type 2 diabetes." (PMID 33750795, 2021). "Genes that increased EIIIA inclusion when deleted included Type II diabetes (KEGG), Stat3, and Stat5 signaling pathways, all of which are linked to insulin signaling responses." (PMID 34615942, 2021). "Type 2 diabetes (T2D) is a metabolic disease that, ultimately, results from insufficient insulin secretion to compensate for peripheral insulin resistance." (PMID 34571945, 2021). "In obesity, skeletal muscle exhibits dysregulation of insulin signaling, glucose uptake, lipid metabolism, and mitochondrial function, thus, driving type 2 diabetes." (PMID 33433056, 2021). "Twenty one participants (14 men and 7 women, aged 45 ± 11 years) with insulin‐independent type 2 diabetes, and unchanged hypoglycaemic medication for the previous 6 months, were recruited for this non‐randomised interventional study." (PMID 34277987, 2021). "Weight reduction, regular physical activity, and healthy eating habits can improve insulin sensitivity and decrease the incidence of metabolic syndrome, type 2 diabetes, and cardiovascular disease (CVD)." (PMID 33494341, 2021). "MAP4K4 have been involved in focal adhesion dynamics regulation, systemic inflammation, lung inflammation, type 2 diabetes, atherosclerosis, insulin sensitivity, and cancer." (PMID 33668405, 2021). "Of non-insulin dependent patients with type 2 diabetes 56/200 (28%) were unwilling to receive insulin, with 50% citing anticipated pain and “inability to take” needling every day as a key reason (although not clear if this was due to distress or anxiety)." (PMID 34111207, 2021). "CHOP activation is associated with the misfolded and unfolded proteins during ER stress, oxidative stress, and cell death under amplified insulin demand, as in type II diabetes." (PMID 34299638, 2021). "Insulin is crucial in regulating blood glucose, and reduced insulin secretion is a key feature of both type 1 and type 2 diabetes." (PMID 33641671, 2021). "The first GWAS for birthweight shortly followed and one of the first variants identified was at the known type 2 diabetes risk locus in ADCY5, which plays a key role in coupling glucose to insulin secretion from the pancreatic beta cell." (PMID 33569631, 2021). "Chronic insulin treatment is required in approximately 25% of patients with type 2 diabetes to control hyperglycemia." (PMID 34158057, 2021).
type 2 diabetes (continued). "Insulin therapy is the cornerstone of treatment for patients with type 2 diabetes who fail to obtain target glycemic control with oral hypoglycemic agents or for patients who are contraindicated for oral hypoglycemic agents." (PMID 33544081, 2021). "OXM acutely improves glucose metabolism in both rodents and humans by significantly increasing insulin secretion and lowering glucose levels even in type 2 diabetes patients." (PMID 34680059, 2021). "To extend our observation onto type II diabetes, we established db/db mice receiving insulin treatment." (PMID 34803500, 2021). "It has been proposed that sesamin plays a role in glucose uptake, carbohydrate metabolism, and insulin signal transduction pathways by controlling the expression of relevant genes in type 2 diabetic rats." (PMID 34707665, 2021). "Foxo1 is a key regulator that mediated by insulin under physiological conditions in type 2 diabetic mice." (PMID 34899339, 2021). "The pathogenesis of type 2 diabetes mellitus (T2DM) includes relatively insufficient insulin secretion and insulin resistance." (PMID 33817307, 2021). "Aerobic exercise promotes mitochondrial ROS generation and increases insulin sensitivity of skeletal muscle in type 2 diabetes, which suggests that ROS involve importantly in insulin signaling regulation in skeletal muscle." (PMID 33795530, 2021). "Since then, advances in research investigating the role of genetics affecting insulin secretion and action have furthered knowledge of fetal insulin-mediated growth and the biology of type 2 diabetes." (PMID 33569631, 2021). "In the third trimester of pregnancy, this insulin resistance in many women reaches a level similar to that observed in type 2 diabetes, requiring the beta-cell to increase its insulin secretion considerably to compensate." (PMID 34388220, 2021). "Current treatments for type II diabetes combine diet therapy, exercise therapy, and pharmacological therapy with hypoglycaemic agents and insulin." (PMID 33759360, 2021). "We here summarize the current knowledge on exosome-mediated modulation of the insulin signaling network including its impact on the pathophysiology of type 2 diabetes mellitus (T2DM)." (PMID 34440850, 2021). "In human studies, miR-146a was increased in obese Chinese children and Chinese adults with type 2 diabetes and in functional in vitro and animal model studies increased miR-146a impaired β-cell function and insulin secretion." (PMID 35169383, 2021). "The current commonly espoused view is that “Type 2 diabetes develops when beta-cells fail to secrete sufficient insulin to keep up with demand, usually in the context of increased insulin resistance.”." (PMID 34447776, 2021). "The threshold for the sympathetic and hormonal counterregulatory response is generally elevated in patients with type 2 diabetes, whereas the counterregulatory threshold is normalized when insulin therapy is initiated." (PMID 34085953, 2021). "The insulin treatment for type 1 and many type 2 diabetes patients is highly individualized due to the variety of living habits, dietary habits, education level and compliance." (PMID 34383816, 2021). "High levels of FFAs are accompanied by defective insulin signaling and beta‐cell dysfunction, and type 2 diabetes is often accompanied by elevated plasma FFAs." (PMID 33463892, 2021). "Specific expression of MafA, in the β-cells of obese type 2 diabetic model mice (db/db) recovered their ability to synthesize insulin, and improved GSIS accompanied with blood glucose amelioration." (PMID 33918379, 2021). "We will initially focus on insulin and glucagon signaling pathways which are deregulated in type 2 diabetes." (PMID 34319011, 2021). "Although this disease is multifactorial, this chronic condition is characterized by the development of hyperglycemia due, in part, to the insufficient production of (Type 1 Diabetes; T1D) or response to (Type 2 Diabetes; T2D) insulin." (PMID 34877823, 2021).
type 2 diabetes (continued). "Circulating levels of CgA and pancreastain are high in type 1 and type 2 diabetes, respectively, because CgA is one of pathogeneses of type 1 diabetes, and pancreastatin induces insulin hyposecretion and insulin resistance." (PMID 34204153, 2021). "Physical and biochemical variables that significantly associated with fibrosis in univariable analysis were included in the ‘Biomarker model’ (sex, WHR, HbA1c, insulin, triglycerides, MetS, type 2 diabetes)." (PMID 33429859, 2021). "Following the MR blockade, the achieved insulin concentration was lower during clamp stage 1 in the individuals with type 2 diabetes compared to healthy controls (p = 0.02)." (PMID 34350730, 2021). "Type 2 diabetes, generally resulting from resistance to insulin, is the most common form of the disease." (PMID 34200160, 2021). "In this study, we used lentivirus to silence Cav-1 in type 2 diabetic mice and investigated the effect of Cav-1 depletion on insulin sensitivity, PI3K p110 expression, and AKT activation after glargine treatment." (PMID 34917687, 2021). "Twenty-one patients with insulin-treated type 2 diabetes (3–36 years of duration) were included in the study." (PMID 34952579, 2021). "The benefits of exercise on insulin sensitivity are also well described, with a meta‐analysis suggesting a 0.6% reduction of HbA1c with exercise in patients with type 2 diabetes." (PMID 33855209, 2021). "Any abnormality in the metabolism of glucose, lipid, and insulin is seen as a classic condition in type 2 diabetes mellitus." (PMID 33916183, 2021). "This management is particularly possible in type 2 diabetes patients with somewhat reserved endogenous insulin secretory capacity, as with the case management of alcoholic ketoacidosis, a sub-type of euglycemic ketoacidosis." (PMID 34123681, 2021). "Type 2 diabetes is a complicated, chronic, and multi-factor disease, featured by prolonged high glucose levels, altered insulin sensitivity, pancreatic beta cell dysfunction, and alterations in oxidative and inflammation-related gene expression." (PMID 35087408, 2021). "Both before and following the MR blockade, baseline insulin sensitivity was lower in the individuals with type 2 diabetes compared to healthy controls (before: p = 0.03, after: p = 0.02)." (PMID 34350730, 2021). "Propionate exerts immunosuppressive actions, increase satiety, regulate fat synthesis and cholesterol in the liver, and improves tissue insulin sensitivity preventing obesity and type 2 diabetes." (PMID 34574197, 2021). "This high lactate levels along with high insulin can be considered as a triggering factor for the further progression of hyperinsulinemia to type 2 diabetes and related complications." (PMID 33708999, 2021). "Type 2 diabetes, commonly arising in elderly and obese patients, occurs due to the decreased insulin sensitivity of peripheral tissues, accompanied by defective insulin secretion in pancreatic islet β-cells." (PMID 33995278, 2021). "Previous studies have reported that RBP4 is upregulated in insulin-resistant mice and is upregulated in the serum of patients with obesity or type 2 diabetes, thus affecting insulin signaling." (PMID 33461622, 2021). "A major open question is what drives changes in β-cell function and insulin secretion in type-2 diabetes." (PMID 33146746, 2021). "The onset of type 2 diabetes is preceded by a decrease in insulin secretion, followed by a metabolic disorder due to an increase in insulin resistance." (PMID 34444187, 2021). "Thiazolidinediones (TZDs) are a class of insulin-sensitizing drugs used alongside diet and exercise for treatment of type 2 diabetes." (PMID 34681797, 2021). "In patients with recent-onset type 2 diabetes, subcutaneous injection of exenatide immediately prior to meal consumption (5,384 kJ) significantly reduces serum insulin at 2, 4, 6, and 8 h post-meal." (PMID 34660576, 2021).
type 2 diabetes (continued). "The changes in BW, FBG, and serum insulin induced by HFD + STZ confirmed the induction of type 2 diabetes." (PMID 34039404, 2021). "Accordingly, guidelines recommend SMBG up to 4–10 times daily for adults with type 2 diabetes (T2DM) on insulin." (PMID 34758807, 2021). "Basal insulin is administered daily as a common part of the treatment regimens for patients with type 1 or type 2 diabetes." (PMID 34174848, 2021). "Summary of initiation, titration, and switching instructions for basal insulin analogs in patients with type 2 diabetes, and clinical recommendations from the authors." (PMID 34165382, 2021). "Type 2 diabetes mellitus (T2DM) is a chronic metabolic disorder characterized by reduced insulin action, increased hepatic glucose production, and the development of diabetic vascular complications." (PMID 33736642, 2021). "Although metformin is the recommended primary treatment of type 2 diabetes, the role of insulin cannot be underestimated." (PMID 33921222, 2021). "This method has already been used successfully in type 1 and type 2 diabetes patients, as well as in insulin-treated children with CFRD for guiding safe and effective insulin therapy." (PMID 33807165, 2021). "The present study reported an increased PR and RI without vessel parameter changes, such as vessel diameter, blood velocity, and RBF, in patients with type 2 diabetes with long-term insulin treatment." (PMID 34283877, 2021). "Plasma insulin was significantly increased in obesity, which combined with hyperglycaemia indicating possible type II diabetes." (PMID 33687595, 2021). "We showed that, consistent with our preclinical studies, SVECs from humans with type 2 diabetes and advanced atherosclerosis have blunted serine phosphorylation of eNOS in response to both insulin and IGF-1." (PMID 34420367, 2021). "RGS4 inhibits the release of insulin mediated through beta-cell M3 muscarinic receptors by binding to M3 receptor to form complex in type 2 diabetes." (PMID 33892733, 2021). "Both before and at the end of the treatment with mineralocorticoid blockade, the individuals with type 2 diabetes had a lower insulin sensitivity compared to healthy controls." (PMID 34350730, 2021). "Improvement of insulin sensitivity protected against decreased β-cell function, which helped prevent type 2 diabetes." (PMID 34359426, 2021). "The secretion of insulin regulated by postprandial stimulation and volume of the pancreatic β-cellular mass which is distressed by several mechanisms in type-2 diabetes." (PMID 33882957, 2021). "Decreased insulin secretion secondary to impaired pancreatic beta-cell function is an essential element in the development of abnormal glucose tolerance and type 2 diabetes." (PMID 32944759, 2021). "Some studies reported that SGLT2i improved insulin sensitivity, but the degree of improvement varied among type 2 diabetes patients." (PMID 34059720, 2021). "It is known that physical exercise improves metabolic flexibility also by increasing insulin‐dependent glucose uptake, particularly in individuals with type 2 diabetes." (PMID 33960110, 2021). "Decreased insulin clearance contributes importantly to the high fasting plasma insulin concentrations in individuals with hepatic TG accumulation and normal glucose tolerance as well as early-stage type 2 diabetes." (PMID 33498493, 2021). "In studies with patients with type 2 diabetes, the positive effect of cranberry supplementation on insulin levels, and HOMA-IR have been shown." (PMID 34798892, 2021). "After using it to treat type 2 diabetic mice, it was found that the content of insulin in mice increased." (PMID 34803667, 2021). "Combination of metformin and insulin is considered a valid and well established combination therapy in type 2 diabetes." (PMID 34481498, 2021). "Type 2 diabetes is a metabolic disorder characterized by resistance to insulin, a unique hormone that controls glucose absorption to maintain whole-body glucose homeostasis." (PMID 34203569, 2021).